AHR (aryl hydrocarbon receptor)
Diseases named in the same sentence as AHR in open-access papers (continued):
Sharing a sentence is not in itself a finding about the gene and the disease.
cancer (continued). "The tryptophan (Trp)/aryl hydrocarbon receptor (AHR) pathway has been identified as a key driver of immunosuppressive microenvironment in various cancer types." (PMID 37655051, 2023). "Kyn appears to play a role in immunological and cancer cells through its interaction with the aryl hydrocarbon receptor (AhR) in the cytoplasm." (PMID 36769263, 2023). "The role of KYN seems to be mediated by the interaction with the cytoplasmic aryl hydrocarbon receptor (AhR) in immune and cancer cells." (PMID 36674430, 2023). "The activation of the AhR pathway has been shown to mediate several detrimental effects, such as aggravation of articular diseases, cancer development and endocrine disruption." (PMID 36899825, 2023). "IL4I1 acts as the main regulator of Trp/AHR signaling and promotes the immune evasion of several cancer types, underscoring its significance as a key drug target." (PMID 37655051, 2023). "After more than half a century of research originating from studies on PAH metabolism, our understanding of the role of AhR in cancer development has expanded dramatically." (PMID 37696458, 2023). "In this section, we have provided a summary of different mechanisms that enable us to gain insights into the complicated interaction between AhR and epigenetic machinery in the regulation of cancer." (PMID 37830596, 2023). "Rather than investigating tumors based on historically evolved characteristics including their tissue of origin or established molecular markers, we propose to identify subgroups of cancers, in which AHR mediates similar functions." (PMID 37696456, 2023). "In TNBC cell models, it was found that PTK6 mediated cancer phenotypes via the AhR and ras homolog gene family, member A (RhoA) activation." (PMID 36831661, 2023). "In the following sections, we will discuss the potential involvement of AhR and PAHs at different stages of cancer development and progression." (PMID 37696458, 2023). "High level of AHR in cancers of lung, breast, esophagus, kidney, and uterus predicts better overall survival of the patients, whereas survival probability of lower AHR cancers is significantly poorer." (PMID 37151890, 2023). "The main aim of discussion related to AhR targeting is to expand the list of pharmacological drugs for effective targeting of AhR-overexpressing cancers." (PMID 37830596, 2023). "AhR is a ligand-activated transcription factor that regulates cell differentiation, proliferation, and cancer imitation." (PMID 37048160, 2023). "Yet, concerns related to the promiscuity of AhR recognition to ligands and the varying effects of the agonistic and antagonistic compounds on cancer." (PMID 37241719, 2023). "AhR and Nrp1 are both expressed in several cell types including neurons, keratinocytes, and several cancer cell lines." (PMID 38035105, 2023). "Increased uptake and catabolism of Trp results in the accumulation of Kyn that enables cancer cell proliferation in part through AhR-signaling." (PMID 37876966, 2023). "Therapeutic targeting of the receptor requires insights into the molecular mechanisms that lead to tumor suppression, the determinants of the response to AhR ligands, and the cancer types that are responsive to AhR-selective modulators." (PMID 37106727, 2023). "A high degree of complexity has emerged in the context of the multifaceted role of AhR in cancer, with a series of outstanding questions related to the cancer promoting and cancer suppressive activities of AhR signaling in studies." (PMID 37830596, 2023). "Mechanistically IL4I1-mediated generation of indole metabolites and KAT-derived KA that activated AhR signaling to promote cancer cell motility and suppression of adoptive immunity." (PMID 37876966, 2023). "These apparently discrete mechanisms have to be viewed as a multi-dimensional perspective to comprehensively analyze the mechanisms of AhR in the inhibition/prevention of cancer." (PMID 37830596, 2023).
cancer (continued). "Our findings provide new insights into both the nature of the interplay between the HIF and AHR pathways and its implications for their therapeutic manipulation in cancer." (PMID 36725335, 2023). "Pulmonary metastatic nodules were lower in number and smaller in size in animal models injected with AhR-silenced MDA-MB-231 cancer cells." (PMID 37830596, 2023). "These divergent effects of the AHR in cancer likely stem from the complexity of its activation and effects, which are cell type-, ligand- and context-specific but are poorly defined." (PMID 37696456, 2023). "Recent studies into AhR have shown that in BC, AhR can promote chemotherapeutic resistance in cancer stem cells and aggressive BC phenotypes via the Wnt5a/β-catenin signaling pathway." (PMID 36831661, 2023). "Thereafter, Kyn was shown to be an endogenous oncometabolite that induces the expression of growth-promoting genes in an AHR-dependent manner in several other cancers such as colon and breast." (PMID 37607000, 2023). "In contrast to the promiscuity of AhR, the selectivity of certain ligands has been demonstrated in different cancer cell lines." (PMID 37241719, 2023). "AhR represents a therapeutically viable cancer target, as select AhR ligands can inhibit the proliferation and migration of cancer cells, induce cellular differentiation, and promote apoptosis." (PMID 37106727, 2023). "Previous studies have shown that the expression of AhR is increased in many cancers, for instance, stomach, liver, prostate, head and neck, breast, brain, and skin cancers." (PMID 37999261, 2023). "Combinatorial strategies consisting of epigenetic-modifying drugs and AhR antagonists will be helpful in realistic and evidence-based results for cancer inhibition." (PMID 37830596, 2023). "It was reported that AHR was highly expressed in many types of human malignant tumor tissues and cell lines and was involved in the occurrence of tumors." (PMID 36829212, 2023). "Different clinical trials are currently being conducted using AhR inhibitors and PD-1 inhibitors (Pembrolizumab and nivolumab), which confirm the linchpin role of AhR-related mechanistic details in cancer progression." (PMID 37830596, 2023). "There was a significant increase in the metastatic spread in mice orthotopically implanted with AhR-silenced H1975 cancer cells in the lungs." (PMID 37830596, 2023). "The aryl hydrocarbon receptor (AhR) is a ligand-activated transcription factor involved in a wide range of developmental, physiological, and disease processes, including cancer." (PMID 37106727, 2023). "The pro-tumorigenic versus antitumor effects of AhR should also be considered in light of the cancer stage." (PMID 37106727, 2023). "This article reviews advances of AhR in cancer research covering publication from 2012 to early 2023." (PMID 37241719, 2023). "Yet, AhR offers a valuable opportunity to develop cancer-specific and/or cell-specific AhR-dependent therapies." (PMID 37241719, 2023). "In parallel, formate activates the aryl hydrocarbon receptor (AhR) signaling pathway, so as to promote cell migration and elicit cancer stem cell traits, including high metastatic capacity and active Wnt signaling." (PMID 37174049, 2023). "Trp/AHR pathway has been proven to drive immunoinhibitory microenvironment in cancers, and is considered to be a hotspot for drug development in cancer combination immunotherapy." (PMID 37655051, 2023). "As discussed in previous sections, inhibition of AhR functions by antagonists as a therapeutic potential has been investigated in different cancers and several mechanisms have been proposed." (PMID 37241719, 2023). "We summarize the structure and pathways of AhR, its roles in cancer, and the ligand-mediated modulation of AhR functions in different cancers with special emphasis on synthetic, pharmaceutical, and natural Ahr ligands." (PMID 37241719, 2023).
cancer (continued). "Chronically active AHR is capable of driving cancer cell invasion, migration, cancer stem cell characteristics and survival." (PMID 37511453, 2023). "The evolutionarily conserved function of AhR in directing development and differentiation is mirrored in cancer cells, where the expression and activation of AhR can negatively regulate the proliferation of stem cell and control cell fate." (PMID 37106727, 2023). "In this section, we have selected key findings for discussion related to regulation of ubiquitin ligases by AhR in different cancers." (PMID 37830596, 2023). "In different cancer types and genetic models, AhR has been shown to negatively regulate signaling pathways and factors which promote tumorigenesis." (PMID 37106727, 2023). "Evidence of dysregulated tryptophan-kynurenine axis in cancer has been reported; the key is aryl hydrocarbon receptor (AhR), a transcription factor modulating cytochrome P450s." (PMID 38053135, 2023). "An increased expression of both IDO1 and IDO2 has been observed in various types of cancer including an AhR-mediated expression of IDO2 in the human mammary epithelial cell line MCF10A." (PMID 37408267, 2023). "In the context of targeting specific proteins in cancer cells by exogenous compounds, aryl hydrocarbon receptor (AhR), a ligand-activated transcription factor, exemplifies a unique pleiotropic target." (PMID 37241719, 2023). "Accumulating evidence has suggested modulation of AhR signaling by agonistic or antagonistic compounds as a valuable therapeutic strategy to control cancer development and progression." (PMID 37241719, 2023). "Nonetheless, the expression and activation of AhR can inhibit the proliferation, migration, and survival of cancer cells, and many clinically approved drugs transcriptionally activate AhR." (PMID 37106727, 2023). "Nonetheless, there is increasing evidence that chronic and sustained activation of AhR by environmental toxins (e.g. dioxins and PAHs) promotes carcinogenesis by supporting cancer stemness, chemoresistance and metastasis." (PMID 37696458, 2023). "While numerous studies have investigated the regulatory effects of the IDO-KYN pathway, the importance of the aryl hydrocarbon receptor (AHR) as a cancer regulator has garnered increasing attention." (PMID 37760608, 2023). "Here, we show that AHR is a direct substrate of PLK1 and that phosphorylation of AHR in LUAD promotes epithelial–mesenchymal transition (EMT) to enhance the metastatic potential of cancer cells." (PMID 37988371, 2023). "Continued research in this field will deepen our knowledge of AHR biology and shed light on its therapeutic potential in cancer and beyond." (PMID 37696456, 2023). "In the context of CRC, deficiency in adenomatous polyposis coli (APC) results in TCF4/β-catenin-mediated upregulation of the TDO2-Kyn-AhR axis to increase glycolysis and drive anabolic cancer cell growth." (PMID 37876966, 2023). "UCHL3 is an effective pharmacological target to block AhR-driven signaling during cancer progression." (PMID 37830596, 2023). "On the other hand, IFN-γ can mediate cancer cell dormancy via the indoleamine-2,3-dioxygenase/kynurenine/aryl hydrocarbon receptor (AhR)/p27 pathway in a STAT1-independent manner." (PMID 37173977, 2023). "Given the important role of HIF and AHR as regulators of cancer progression, therapeutic inhibitors have now been developed to target each pathway." (PMID 36725335, 2023). "The effects of aberrant tryptophan metabolism on the AHR can promote inflammatory diseases and cancers." (PMID 37394584, 2023).
cancer (continued). "Recently, hexokinase 2 (HK2), an important enzyme for cancer growth, has been reported as an AHR target gene that modulates AHR activity by promoting AHR promoter demethylation." (PMID 37696456, 2023). "IL-22 initiates DNA damage response in epithelial stem cells via aryl hydrocarbon receptor (AHR)sensing of genotoxic phytochemicals, preventing malignant transformation and cancer development." (PMID 37122757, 2023). "Elucidating these mechanisms will allow the identification of new targets for treating AhR-positive cancer." (PMID 37056388, 2023). "The p-hydroxycinnamic acid inhibited cancer progression partly through the activation of AhR signaling." (PMID 37830596, 2023). "Overexpression of AhR in many cancers triggers production of toxic metabolites via overexpression of CYP1A1 and CYP1B1." (PMID 36160406, 2022). "Intriguingly, activation of the AhR signaling pathway has previously been correlated with the radioresistance, and AhR knockout suppresses the malignant phenotypes of cancer cells." (PMID 35918714, 2022). "Reports suggest that a major pathway that regulates xenobiotic detoxification is the aryl hydrocarbon receptor (AhR) pathway, whose involvement in several cancer and cancer stem cells (CSCs) was recently demonstrated." (PMID 35742838, 2022). "recently identified IL4I1 as a major aryl hydrocarbon receptor (AHR)-activating enzyme that promotes AHR-driven cancer cell motility and suppresses adaptive immunity." (PMID 36466837, 2022). "The tryptophan metabolite kynurenine is an interesting endogenous AhR agonist that is elevated in chronic diseases such as cancers and neurological disorders." (PMID 36499198, 2022). "Another link of AhR with immune response in cancer is highlighted by the fact that AhR mediates the induction of the poliovirus receptor CD155 by IL-4 and LPS in macrophages, as CD155 is suppressing T cell function." (PMID 36588678, 2022). "The role of KA (and KAT) in AhR activation merits investigation in future cancer-related studies for a number of reasons." (PMID 36286592, 2022). "We were able to rescue the effects of formate on CRC cell invasion with an AhR inhibitor, suggesting that Fn-derived formate induces cell invasion by activating AhR-induced cancer stemness." (PMID 35437333, 2022). "We also observed a higher number of OCT4-positive cells in the colons of Fn-treated mice compared to the control, indicating increased cancer stemness, potentially driven by AhR." (PMID 35437333, 2022). "Based on previous documentation on UCHL3 maintaining NSCLC cancer cell stemness by stabilizing AhR protein level via deubiquitination, we then determined AhR protein with immunohistochemistry." (PMID 35918714, 2022). "In hematologic cancer, AhR activation using FICZ not only improves the ability of NK cells to produce IFN-γ and cytolytic activity, but also enhances the ability of NK cells to inhibit cancer growth in an AhR-dependent manner." (PMID 36110860, 2022). "As a ligand-activated transcription factor, AhR enables cells to adapt to changing environments and exerts a critical role in the development of cancer." (PMID 36258210, 2022). "The high enzyme activity of KP has been proposed to trigger anti-inflammatory and immunosuppressive mechanisms, thereby executing pathological functions such as activation of cancer and aromatic hydrocarbon receptor (AHR)." (PMID 35296014, 2022). "In this vein, O’Donnell and others have pursued SMAhRTs, Select Modulators of AhR-regulated Transcription, to specifically exploit the anti-cancer functions of AhR." (PMID 36588678, 2022). "The indoleamine 2,3-dioxygenase 1 (IDO1) metabolic circuitry, comprising the first tryptophan (Trp) catabolite L-kynurenine (Kyn) and the aryl hydrocarbon receptor (AHR), has emerged as a mechanism of cancer immune evasion." (PMID 35371054, 2022).
cancer (continued). "In recent years, there has been increasing evidence that the aryl hydrocarbon receptor (AhR) plays a major role in tumorigenesis and makes the AhR an interesting pharmacological target in cancer treatment." (PMID 36500264, 2022). "Interestingly, IKKα may directly interact with the AhR and this cross-talk has been proposed to mediate chromatin remodeling, which might alter both the AhR-dependent transcription and expression of genes linked with stem-like properties of cancer cells." (PMID 35203356, 2022). "Several reports correlate cancer occurrences with exposure to xenobiotics via induction of a protein receptor named aryl hydrocarbon receptor (AhR)." (PMID 35742838, 2022). "In this model, expression of CYP1B1 is viewed as a surrogate or biomarker of AHR signaling and hence the activity of this cancer progression circuit." (PMID 36077068, 2022). "While the activation of AhR by xenobiotics leads to different cancers in mammals, dietary and environmental factors were shown to have opposite AhR-dependent effects on C. elegans’ health span." (PMID 35453298, 2022). "Only nine of these compounds exhibited both in vitro and in vivo activity as AhR agonists in the complete panel of assays which included cytochrome P450 induction in mouse cancer cell lines and liver (in vivo)." (PMID 36428667, 2022). "In non-small cell lung carcinoma, the deubiquitinase UCHL3 promoted cancer stemness through stabilization of AhR." (PMID 36588678, 2022). "To date, the evaluation of IDO1 inhibitors alone or combined with ICI in clinical trials have provided disillusioning results, requiring more comprehensive understandings on the role of Trp-Kyn-AhR pathway in cancer development and immunology." (PMID 35173722, 2022). "Wnt5 also controls IDO1 activity in DC via β-catenin signaling while maintaining continuous expression in several cancer cell lines via an AhR-IL-6-STAT3 (Signal Transducer And Activator Of Transcription 3) signaling loop, according to new research." (PMID 35918736, 2022). "Nuclear localization of AhR and induction of its downstream genetic program are recurrently detectable in a large panel of cancers." (PMID 35681770, 2022). "Seven human OC cell lines have been utilized in the current study to initially investigate and correlate the expression patent of AhR and regulated genes with the aggressiveness of cancer." (PMID 35742838, 2022). "Nevertheless, the collective evidence strongly suggests that AhR activation by environmental toxins and endogenous ligands aligns with chemoresistance, recurrence and metastasis, the hallmarks of cancer stemness." (PMID 36588678, 2022). "Overall, these findings are exciting in terms of therapeutic utility of AhR as a target of interest for proteasomal degradation in inflammatory diseases or certain cancers where endogenous overactivation of the AhR is consistently reported." (PMID 35626744, 2022). "Accumulating evidence highlights the role of AhR in cancer development encompasses both pro- and anti-tumorigenic activities." (PMID 36258210, 2022). "Here, we describe the identification of novel recurrent exon-deleting AHR alterations in the pan-cancer whole-genome sequencing database of metastatic cancers from Hartwig Medical Foundation." (PMID 35710704, 2022). "Kyn is an oncometabolite that activates the aryl hydrocarbon receptor, a transcription factor that regulates progrowth genes, and Kyn also inhibits T-cell activity, which promotes cancer cell immune evasion." (PMID 36232383, 2022). "The AhR is a significant regulator of platelet development and primed activation, indicating a role for cancer cell kynurenine release in platelet activation." (PMID 36613754, 2022). "More recently, AHR has gained significant interest as a drug target for the development of novel cancer immunotherapy drugs." (PMID 36266304, 2022).